ENSG00000254051 (NADH dehydrogenase )
Gene: Processed pseudogene on chromosome 8 (68,176,768 to 68,177,221, forward strand). Ensembl gene ENSG00000254051.
Diseases named in the same sentence as ENSG00000254051 in open-access papers:
ENSG00000254051 is named in the same sentence as 93 diseases in open-access papers, as found by Europe PMC text mining. Sharing a sentence is not in itself a finding about the gene and the disease. The quoted sentences say what the papers report.
breast carcinoma (10 papers, 2009 to 2025). "In mtSNP-subset analysis, the gene MT-CO2 (P = 0.001, q = 0.09) in Complex IV (cytochrome c oxidase) and MT-ND2 (P = 0.004, q = 0.19) in Complex I (NADH dehydrogenase (ubiquinone)) were significantly associated with breast cancer risk." (PMID 31577800, 2019). "Our study encourages the development of compounds that inhibit NADH dehydrogenase for a personalized therapy against HR(+)/HER2(−) breast cancer." (PMID 39873399, 2025). "NDUFB9 is a component of NADH dehydrogenase in the respiratory chain complex I. NDUFB9 was downregulated in highly metastatic breast cancer and silencing its expression in MDA-MB-231 cells promotes proliferation, migration, and invasion." (PMID 38283944, 2023). "The enrichment of KIRP is mainly related to the oxidative respiratory chain, in which inhibition of NADH dehydrogenase activity has been proven to promote gastric cancer and breast cancer." (PMID 31850211, 2019). "For example, enhancement of complex I activity through NADH dehydrogenase expression strongly interferes with tumor growth and metastasis, while inhibition of complex I enhances the metastatic potential of already aggressive breast cancer cells." (PMID 25546457, 2014).
Parkinson disease (8 papers, 2012 to 2025). A progressive degenerative disorder of the central nervous system characterized by loss of dopamine producing neurons in the substantia nigra and the presence of Lewy bodies in the substantia nigra and locus coeruleus. "Ksel found a heteroplasmic mtDNAG5460A missense mutation in the ND2 subunit gene of NADH dehydrogenase was three times more frequent in Parkinson cases (4/21) compared to controls (5/77)." (PMID 39789452, 2025). "NDUFC2, the most significant novel gene from brain tissue, encodes a subunit of the mitochondrial membrane respiratory chain NADH dehydrogenase that is associated with mitochondrial diseases including Parkinson’s disease." (PMID 33809961, 2021). "NADH dehydrogenase is the first enzyme of the mitochondrial electron transport chain, and disruption of this pathway has been implicated in Parkinson’s disease." (PMID 22912838, 2012).
diabetes (5 papers, 2007 to 2023). "It has also been described, that impaired activity of the NADH dehydrogenase, due to pathogenic mtDNA mutation, occurs in people with type 2 diabetes mellitus." (PMID 36860523, 2023). "Metformin is an approved drug for the treatment of type 2 diabetes mellitus (DM) and is known to be a reversible inhibitor of mitochondrial NADH dehydrogenase, resulting in lower ATP production." (PMID 35740222, 2022). "NDUFA4, formerly known as a constituent of NADH dehydrogenase, was recently identified as a component of the CIV complex associated with mitochondrial dysfunction, syndromic obesity, and the development of diabetes." (PMID 32258168, 2020). "Genes involved in NADH dehydrogenase (ubiquinone) activity, glutamate dehydrogenase [NAD(P)+] activity, transposase activity, guanylate cyclase inhibitor activity were upregulated both in diabetes and obesity." (PMID 18078524, 2007).
Leber hereditary optic neuropathy (5 papers, 2015 to 2025). Leber's hereditary optic neuropathy (LHON) is a mitochondrial neurodegenerative disease affecting the optic nerve and often characterized by sudden vision loss in young adult carriers. "This situation is similar to the organ specific effect of mutations in mt tRNAIle, which primarily cause hypertrophic cardiomyopathy and of mutations in NADH dehydrogenase causing Leber’s hereditary optic neuropathy." (PMID 28267784, 2017). "This gene is one of the seven mitochondrial genes encoding for subunits of NADH dehydrogenase where variants in this gene have previously been associated with Leber optic atrophy, mitochondrial complex 1 deficiency, and Leigh syndrome due to mitochondrial complex deficiency." (PMID 35699875, 2022). "Leber Hereditary Optic Neuropathy (LHON) mostly occurs as a result of one of the three-point mutations in mtDNA located at nucleotides 11,778, 14,484 and 3460, all affecting the NADH dehydrogenase (ND) subunits of complex I of the electron transport system (ETS)." (PMID 39858655, 2025).
Alzheimer disease (4 papers, 2019 to 2023). A progressive, neurodegenerative disease characterized by loss of function and death of nerve cells in several areas of the brain leading to loss of cognitive function such as memory and language. "As a case in point, excitatory neurons and inter-neurons down-regulate genes encoding subunits of the NADH dehydrogenase early in the course of Alzheimer’s disease, a phenomenon that can be imaged with [18F]FP1OP, originally developed for cardiac imaging." (PMID 37957176, 2023). "On the contrary, in the cerebral cortex, energy metabolism (oxidative phosphorylation, NADH dehydrogenase activity), Alzheimer disease, and retrograde endocannabinoid signaling involve downregulated proteins." (PMID 31201651, 2019).
Leigh syndrome (4 papers, 2012 to 2022). A progressive neurological disease defined by specific neuropathological features associating brainstem and basal ganglia lesions. "NADH Dehydrogenase (Ubiquinone) Fe-S protein 4 (Ndufs4) is one of the subunits of mitochondrial complex I and its mutation in human is associated with Leigh syndrome." (PMID 34040028, 2021). "Patients with Leigh syndrome are carrying specific point mutations in the mitochondrially encoded subunits 1–6 of NADH dehydrogenase, cytochrome c oxidase and ATPase." (PMID 25839158, 2015).
Sepsis (4 papers, 2014 to 2023). Sepsis is defined as life-threatening organ dysfunction caused by a dysregulated host response to infection. "Parkin overexpression also prevented a sepsis-induced decrease in the content of mitochondrial subunits of NADH dehydrogenase and cytochrome C oxidase." (PMID 32545383, 2020). "RPCR targeting a mtDNA-specific gene sequence of NADH dehydrogenase detected a ~1.5-fold-increase of mtDNA that were released into the myocardial cytoplasm in response to sepsis." (PMID 26448624, 2015). "In particular, the prominence of NADH dehydrogenase activity in the top gene networks is consistent with decreased complex I gene expression and activity noted in skeletal muscle in human adult sepsis." (PMID 25410281, 2014). "We observed that the sepsis-alone group and the ARDS group shared 7 enriched GO functions and pathways, and showed concordant regulatory direction, such as neutrophil mediated immunity, NADH dehydrogenase complex assembly and dopaminergic related pathways." (PMID 37443002, 2023).
malaria (3 papers, 2010 to 2019). Malaria is a serious and sometimes fatal disease caused by a parasite that commonly infects a certain type of mosquito which feeds on humans. "In malaria parasites DPI has been shown to inhibit the activity of NADH dehydrogenase-an equivalent of complex I, and effectively inhibit the growth of P. falciparum in cell culture." (PMID 20221395, 2010). "Their data suggested that mitochondria of malaria parasites were able to oxidize NADH and an active NADH dehydrogenase(s) was present." (PMID 30964863, 2019). "In contrast, malaria parasites lack the conventional multi-subunit Complex I. Instead, they have a type II NADH dehydrogenase (NDH2), which is a single subunit, non-proton pumping protein, likely attaching to the mitochondrial inner membrane and facing the mitochondrial matrix." (PMID 30964863, 2019).
myocardial infarction (3 papers, 2020 to 2025). Gross necrosis of the myocardium, as a result of interruption of the blood supply to the area, as in coronary thrombosis. "The finding that Rb1 can bind to NADH dehydrogenase in mitochondrial complex I was also verified in the mice model of acute myocardial infarction." (PMID 40682486, 2025).
Non-alcoholic fatty liver disease (3 papers, 2022 to 2024). "The enrichment analysis results of GO and KEGG indicate that TBRG4 may be related to Non-alcoholic fatty liver disease, Oxidative phosphorylation, structural constituent of ribosome, NADH dehydrogenase (ubiquinone) activity." (PMID 38347489, 2024).
tuberculosis (3 papers, 2012 to 2023). A chronic, recurrent infection caused by the bacterium Mycobacterium tuberculosis. "Combining GaMF1.39 with the NADH dehydrogenase inhibitor clofazimine, the cyt-bcc:aa3 inhibitor Telacebec, or the F-ATP synthase inhibitor TBAJ-876 showed enhanced whole ATP synthesis inhibition and anti-tuberculosis activity." (PMID 37982630, 2023). "tuberculosis also responds to hypoxia in vitro and chronic infection in the mouse lung by switching from a proton-pumping to a non-proton-pumping NADH dehydrogenase." (PMID 23029022, 2012).
colon cancer (2 papers, 2005 to 2012). "Furthermore, NADH dehydrogenase (ubiquinone) has also been determined by others to have a decreased abundance in HT-29 human colon cancer cells following exposure for 24 h to 150 μM quercetin." (PMID 15748282, 2005).
gastric cancer (2 papers, 2019 to 2023). A primary or metastatic malignant neoplasm involving the stomach. "In addition, MF analysis in GO also confirmed that γ-T3 inhibits NADH dehydrogenase activity and oxidoreduction-driven activity of active transmembrane transporters pathways acting in gastric cancer cells." (PMID 37055846, 2023).
glioma (2 papers, 2008 to 2019). A benign or malignant brain and spinal cord tumor that arises from glial cells (astrocytes, oligodendrocytes, ependymal cells). "In a recent study, we described that glycolytic glioma cells are resistant to blockers of the ETC, in particular rotenone, a complex I (NADH dehydrogenase) blocker." (PMID 18985161, 2008).
mitochondrial encephalomyopathies (2 papers, 2015 to 2021). "Mutations in NADH dehydrogenase (ND) subunits of complex I lead to mitochondrial encephalomyopathies associated with various phenotypes." (PMID 25550170, 2015).
Obesity (2 papers, 2007 to 2021). Accumulation of substantial excess body fat. "We identified several variants of the NADH dehydrogenase subunit that were significantly positively or negatively correlated with risk of obesity." (PMID 33659027, 2021). "NADH dehydrogenase is required for energy generation in the cell; therefore, variants within its seven encoding genes could result in metabolic disorders including obesity." (PMID 33659027, 2021).
schizophrenia (2 papers, 2011 to 2019). A major psychotic disorder characterized by abnormalities in the perception or expression of reality. "For example, NADH dehydrogenase was up-regulated here and has previously been reported as upregulated in schizophrenia posterior hippocampal post-mortem samples but reduced in anterior hippocampus." (PMID 21347362, 2011).
amyloidosis (1 paper, 2017). A disorder characterized by the localized or diffuse accumulation of amyloid protein in various anatomic sites. "In cells undergoing WH1(A31V)-mCh amyloidosis, the only differentially induced NADH-dehydrogenase at the early stage was NdhII (encoded by ndh)." (PMID 28421043, 2017).
anaemia (1 paper, 2018). "Future studies with a larger sample size are needed to verify whether or not NADH dehydrogenase mutations might contribute to intolerance to severe anaemia." (PMID 30545357, 2018).
Arthritis (1 paper, 2019). Inflammation of a joint. "The diminution of NADH dehydrogenase caused by arthritis amounted to 31%." (PMID 31618993, 2019). "In addition to isocitrate dehydrogenase, adjuvant-induced arthritis also modified the activities of other respiratory enzymes, namely NADH dehydrogenase, L-malate dehydrogenase and succinate dehydrogenase." (PMID 31618993, 2019).
asthenozoospermia (1 paper, 2022). "-Removal of several mitochondrial genes: ATP8 (lost with 7599 bp only), ATP6, cytochrome oxidase (COX) III, cytochrome b (CYB), NADH dehydrogenase (ND) 3,4, 4L, 5, and 6.-Reduction in the obtained energy, which in turn has a negative effect on sperm flagellum movement and leads to asthenozoospermia." (PMID 35885965, 2022).
bipolar disorder (1 paper, 2021). A disorder of the brain that causes unusual shifts in mood, energy, activity levels and the ability to carry out day-to-day tasks. "Deficits in the electron transport chain complex proteins I and IV, NADH dehydrogenase and c-oxidase, respectively, were dysregulated in both AD and bipolar disorder, along with a host of other neuropsychiatric complications." (PMID 33920138, 2021).
cyst (1 paper, 2022). A sac-like closed membranous structure that may be empty or contain fluid or amorphous material. "While we show that in vitro bradyzoites develop tolerance toward the dual alternative NADH dehydrogenase and DHOD inhibitor HDQ43,68, other mETC inhibitors, such as atovaquone appear to have some effect and lead to a decrease in cyst counts in brains of latently infected mice." (PMID 35246532, 2022).
Desminopathy (1 paper, 2024). "GSEA identified overall downregulated mitochondrial-related pathways such as the tricarboxylic acid cycle, mitochondrial electron transport, and NADH dehydrogenase activity, which was similar to desminopathy." (PMID 39239540, 2024).
dilated cardiomyopathy (1 paper, 2022). Cardiomyopathy which is characterized by dilation and contractile dysfunction of the left and right ventricles. "Specifically, doxorubicin has high affinity towards mitochondrial enzymes such as xanthine oxidase, NADH dehydrogenase, and cytochrome P450 reductase to generate reactive oxygen species during dilated cardiomyopathy." (PMID 38125869, 2022).
Hypoglycemia (1 paper, 2010). A decreased concentration of glucose in the blood. "Deficiencies in seven NADH dehydrogenase genes all lead to hypoglycemia, confirmed in simulation, and a decreased ability to oxidize citrate and glutamate, reactions important for indirect renal reabsorption of citrate and glutamate in the model." (PMID 20957118, 2010).
infarction (1 paper, 2021). A localised pathological necrosis of tissue resulting from obstruction of the blood supply usually by a thrombus, an embolus, or vascular torsion. "Our results showed only discreet effects during the cardiotoxic ISO action on the endogenous cardiac NADH dehydrogenase activity, since only after 2 and 4 days of treatment (in the post-infarction stage), was observed an enhancement and a tendency to increase the maximal NADH oxidation." (PMID 34573076, 2021).
iron deficiency (1 paper, 2011). "To evaluate the magnitude of the imbalance between the fatty acid oxidation and the ETC created by iron deficiency and a high fat diet, we measured the enzyme activities of LCAD and the iron containing, electron transport chain enzyme NADH dehydrogenase." (PMID 21589859, 2011).
left ventricular hypertrophy (1 paper, 2023). Enlargement of the LEFT VENTRICLE of the heart. "A dysfunction of NADH dehydrogenase, the mitochondrial Complex I (CI), associated with the development of left ventricular hypertrophy (LVH) in previous experimental studies." (PMID 37558995, 2023).
liver cancer (1 paper, 2025). An epithelial or non-epithelial malignant neoplasm that arises from the liver. "Among the activities of the ETC complexes, the NADH dehydrogenase activity of CI was critical for cell proliferation in breast and liver cancer cells." (PMID 39873399, 2025).
lung adenocarcinoma (1 paper, 2015). A carcinoma that arises from the lung and is characterized by the presence of malignant glandular epithelial cells. "In lung adenocarcinoma cell line (A549), nonsense and missense mitND6 gene mutations resulted in significant decrease in NADH dehydrogenase activity, increases in ROS production and promoted cell migration and invasion." (PMID 25934296, 2015). "Since ND6 is a subunit of the NADH dehydrogenase, we detected the effect of mitND6 gene nonsense and missense mutation on the activity of NADH dehydrogenase in lung adenocarcinoma cells." (PMID 25934296, 2015). "Hence, mitND6 gene nonsense and missense mutation resulted in reduced NADH dehydrogenase activity in lung adenocarcinoma cells." (PMID 25934296, 2015). "Our data suggest that mitND6 gene nonsense and missense mutation might promote cell migration and invasion in lung adenocarcinoma, probably by NADH dehydrogenase deficiency induced over-production of ROS." (PMID 25934296, 2015). "Based on these findings, we propose that mitochondrial ND6 gene nonsense and missense mutation may contribute to the metastasis of lung adenocarcinoma by reducing the activity of NADH dehydrogenase and in turn the over-production of ROS probably through AKT and ERK1/ERK2 signal pathway." (PMID 25934296, 2015).
lung carcinoma (1 paper, 2023). "A substantial decrease in the activity of NADH dehydrogenase and complex I protein content has been reported in renal and lung cancer, and a reduction in the activity of complex I was also reported in thyroid cancer which was related to ND1 gene." (PMID 37482618, 2023).
multiple myeloma (1 paper, 2025). "Within this pathway, the cyclooxygenase and NADH dehydrogenase (NDUF) gene families comprised many of the genes expressed at a higher level in LCE-multiple myeloma, also factors associated with worse survival." (PMID 39699274, 2025).
neuroblastoma (1 paper, 2025). Neuroblastoma (NB) is the most common solid, extracranial childhood tumor. "Nevertheless, previous study reported that MT1A tranduced into the mitochondria of MPP+-treated SH-SY5Y neuroblastoma cells was able to alleviate mitochondrial damage, as shown by restored ATP levels, mitochondrial NADH dehydrogenase activity and mitochondrial superoxide levels." (PMID 39959428, 2025).
neuropathy (1 paper, 2024). A disorder affecting the nervous system that manifests with pain, tingling, numbness, and/or muscle weakness. "The mt-Nd3 and mt-Nd4l genes predict the activation of NADH dehydrogenase (ubiquinone) activity in mitochondria, which is associated with mitochondrial function and regulation of neuropathy." (PMID 39796522, 2024).
pancreatitis (1 paper, 2025). Inflammation of the pancreas. "Single-cell transcriptomic profiling (GSE188819) revealed significant enrichment of the NADH dehydrogenase activity pathway (FDR<0.01) in pancreatitis-associated macrophages, mechanistically linking mitochondrial ROS generation to disease progression." (PMID 41208897, 2025).
papillary thyroid carcinoma (1 paper, 2021). "The results showed that the expression levels of NADH dehydrogenase, ATP synthetase 6, cytochrome oxidase B, and cytochrome oxidase I and III genes are upregulated in papillary thyroid carcinoma, whereas the expression of nuclear encoded mtTFA is not significantly changed." (PMID 34568328, 2021).
Pleural effusion (1 paper, 2025). The presence of an excessive amount of fluid in the pleural cavity. "For pleural effusion, BL and EP tumor cells had higher expression of mitochondria-associated genes, such as CO (cytochrome C oxidase), ND (NADH dehydrogenase), and ATP6, while LP cells expressed EMT-associated genes, such as YEATS4, MDM2, and RGS5." (PMID 39955556, 2025).
toxoplasmosis (1 paper, 2021). A parasitic disease contracted by the ingestion or fetal transmission of toxoplasma gondii. "In addition, the present study detected several points of mutation of mtDNA including NADH dehydrogenase (ND1, ND4) and Cyt B genes and the nDNA pyruvate kinase (PK) gene for autistic children infected with toxoplasmosis." (PMID 33731054, 2021).
type 1 diabetes (1 paper, 2022). "The aim of the study was to evaluate the presence of Complex I in serum by measuring NADH dehydrogenase [ubiquinone] iron–sulfur protein 8 serum level, and the relationship with insulin resistance in type 1 diabetes." (PMID 36135178, 2022).